IL1B (interleukin 1 beta)
Diseases named in the same sentence as IL1B in open-access papers (continued):
Sharing a sentence is not in itself a finding about the gene and the disease.
periodontal disease (continued). "IL-1β is a pro-inflammatory cytokine involved in the pathogenesis of periodontal disease related to inflammation, connective tissue breakdown, and bone loss." (PMID 33092290, 2020). "Depending on the stage of periodontal disease progression, the biomarkers in saliva with high linkage are IL-1β in the immunologic phase and MMP-8 in the inflammatory phase." (PMID 33383828, 2020). "The biomarkers showing elevated levels in the baseline saliva of patients with periodontal disease were IL-1β, IL-4, IL-6, MMP-8, and TIMP-2, while the control group showed high levels of TNF-a, IL-10, IL-17, and IL-32." (PMID 33383828, 2020). "Regarding lymphocytes, a study supports the role of SCFA, particularly butyrate, in the pathogenesis of periodontal diseases by suppressing T-cells proliferation and increasing IL-1β production by monocytes." (PMID 32664466, 2020). "Analyses of GCF samples from 100 individuals over 12 months have indicated that IL1β is a potential biomarker that can predict periodontal disease progression." (PMID 33081038, 2020). "During periodontal disease, host inflammatory cells are recruited, and inflammatory cytokines, such as IL-1β, IL-6, and TNF-α, are released from fibroblasts, macrophages, connective tissue, and junctional epithelial cells." (PMID 33383828, 2020). "C5a was found to increase the release of IL-1β and IL-6 when added to Aβ-primed human monocytes in vitro and C5aR1 antagonists have been found to reduce proinflammatory cytokines (IL-1β) in periodontal disease." (PMID 33239010, 2020). "Biomarkers showing high levels in periodontal disease were salivary IL-1β, IL-4, IL-6, MMP-8, and tissue inhibitor of matrix metalloproteinases (TIMP)-2, and those in the controls were tumor necrosis factor (TNF)-α, IL-10, IL-17, and IL-32." (PMID 33383828, 2020). "It has been reported that the levels of IL-1α, IL-1β and also IL-1/IL-receptor antagonist (RA, anti inflammatory cytokine) have been increased in patients with periodontal diseases." (PMID 30755190, 2019). "Studies have shown a strong relationship between the severity of periodontal disease and IL-1β levels in the gingiva and GCF." (PMID 31308830, 2019). "Inflammation is induced by stimulation with not only bacterial components (via TLR) but also IL-1β (via IL-1β signaling) in oral cells, and can exacerbate periodontal diseases." (PMID 30142971, 2018). "IL-1β has been established as a robust GCF biomarker for a hyper-inflammatory phenotype, as well as severe clinical inflammation, bone loss and periodontal disease progression." (PMID 30206230, 2018). "According to our ELLSA results, curcumin inhibited the production of IL-1β and TNF-α in rat gingival fibroblasts induced by LPS, which showed that curcumin has potential role in modulating immune response associated with periodontal diseases." (PMID 30115081, 2018). "Pro-inflammatory mediators, including Il-6, IL-1β and PGE2 are also associated with periodontal disease progression and alveolar bone resorption." (PMID 29075409, 2017). "Periodontal disease mainly occurs as a result of the activation of host‐derived immune and inflammatory mechanisms induced by cytokines, including IL‐1β, IL‐6, and TNF‐α (2009; 1996)." (PMID 29744190, 2017). "Inflammatory biomarkers that have been found to be elevated in the saliva of adult individuals with T2D and periodontal disease include interleukin 1-β (IL-1β) and C-reactive protein (CRP)." (PMID 28253297, 2017). "High levels of IL-1β, and IFNγ, which play key roles in inflammatory immune responses, have been identified in periodontal disease." (PMID 28962660, 2017). "IL-1β is important in periodontal diseases due to its potency in inhibiting bone formation and enhancing bone resorption stimulating the production of prostaglandin E2, collagenase, and proteinase." (PMID 28721329, 2017).
periodontal disease (continued). "Salivary interleukin-1 beta is elevated in periodontal diseases and its levels are strongly correlated with periodontal disease progression and considered to be a good biomarker for discriminating between active and inactive periodontal sites." (PMID 27143814, 2016). "Similar to TNFα, IL-1β is a pro-inflammatory cytokine critical to inflammatory response against pathogens that is well known for involvement in periodontal disease." (PMID 27386246, 2016). "Investigating the interaction between P. gingivalis and host cells leading to inflammasome activation and IL-1β release is necessary to understand the development of periodontal diseases." (PMID 28083517, 2016). "IL-1β can be considered among the most common biomarkers that give precise results and can be used as an indicator of periodontal disease progression." (PMID 28074077, 2016). "According to recent review, interleukin-1 beta and hepatocyte growth factor are the most robust salivary biomarkers for periodontal disease." (PMID 27143814, 2016). "At present, numerous potential surrogate measures of existing periodontal disease and oral health have been identified and include cytokines and MMPs such as interleukin-1β (IL-1β), tumor necrosis factor (TNF)-α, and matrix metalloproteinase (MMP)-8." (PMID 25915398, 2015). "TLR3 stimulation in combination with IL-1β has previously been shown to initiate CCL20 upregulation in human gingival fibroblasts in periodontal disease, and our results indicate that this cellular mechanism can also be important in IBD." (PMID 26536229, 2015). "IL-1β and IL-6 have been identified as the key inflammatory mediators in periodontal disease which lead to connective tissue degradation and alveolar bone resorption." (PMID 25806806, 2015). "Our study suggests that polymorphisms in the IL-4 gene not only affect the production of the IL-4 cytokine but can influence production of several other cytokines, such as IL-10, IFNγ, IL-1β, IL-6, and TNFα, which in turn can affect periodontal disease." (PMID 25530681, 2014). "In the present study, the inflammatory process of periodontal diseases was evaluated for the first time by determining IL-17 and IL-1β serum levels before and after two disinfection techniques of FMD and Q-SRP." (PMID 25512752, 2013). "In patients with periodontal disease, IL-1β expression was elevated in the GCF at sites of recent bone and attachment loss." (PMID 24151615, 2013). "In patients with periodontal disease, monocytes and dendritic cells within local periodontal tissues secrete various inflammatory mediators, including IL-1β, IL-6, and TNF-α." (PMID 23951003, 2013). "To date, two proinflammatory cytokines, TNF-α and IL-1β, are the best understood cytokines that correlate significantly with periodontal diseases." (PMID 22315682, 2012). "The data from this study revealed that treatment with an orally active p38 MAPK inhibitor stopped the established periodontal disease progression in vivo and decreased inflammatory cytokine (IL-1β, TNF-α) expression and osteoclastogenesis." (PMID 22315682, 2012). "For IL-10 and IL-1β, the mean was below the cut-off point in all periodontal disease diagnoses." (PMID 40002786, 2025). "Furthermore, the strong correlation between MMP-8 and IL-1β underscores the relevance of these biomarkers in periodontal disease progression." (PMID 40362854, 2025). "Similarly, in our study, salivary IL-1β concentrations were significantly higher in the periodontal disease groups." (PMID 39964474, 2025). "The first mechanism is supported by the presence of periodontal disease bacteria formed in atherosclerotic lesions in the coronary arteries and the second by the presence of increased levels of IL-1b, IL-6, IL-8 and TNF-a which are cytokines also related to ASCVD26." (PMID 41006734, 2025). "Salivary IL-1β concentrations increase in periodontal disease." (PMID 39964474, 2025).
periodontal disease (continued). "IL-1β levels showed a strong positive correlation with the Gingival Index (r = 0.991, p < 0.001), reflecting its role in driving gingival inflammation during the initial stages of periodontal disease." (PMID 40283051, 2025). "IL-1β is a well-known pro-inflammatory cytokine in periodontal diseases." (PMID 39964474, 2025). "The findings of this study suggest that salivary IL-1β and MMP-8 could be effectively integrated into chairside diagnostic tools for the early detection and staging of periodontal disease." (PMID 40283051, 2025). "For example, a recent study demonstrated that elevated levels of IL-1β, IL-6, and MMP-8 are associated with increased periodontal disease severity among diabetic patients, suggesting a bidirectional relationship between glycemic control and periodontal inflammation." (PMID 40283677, 2025). "It is suggested that greater IL-1β concentrations could be one of the host–response components connected to clinical symptoms of periodontal disease." (PMID 38086426, 2024). "Also, polyphenols showed therapeutic effects on periodontal disease by inhibiting LPS-induced inflammatory cytokines (IL-1β, IL-6, IL-8) in PDL cells." (PMID 39548434, 2024). "There are several examples in the existing research where the IL1B rs1143634 variant was not proven to increase periodontal disease risk." (PMID 38248068, 2024). "Salivary biomarkers such as ALP and IL-1β are critical in diagnosing periodontal diseases." (PMID 39554809, 2024). "The objective of this study was to examine whether, among individuals with PKU and T1DM, those with IL1B rs1143634 and/or DEFB1 rs11362 exhibit a higher susceptibility to the development of periodontal disease compared to healthy controls." (PMID 38248068, 2024). "While periodontal homeostasis is maintained via proinflammatory [i.e. interleukin 1 beta (IL-1β)] and antiinflammatory (i.e. IL-10) cytokine balance, any destabilization beneficial for the proinflammatory cytokines results in periodontal disease, tissue destruction, and/or impaired healing." (PMID 38812655, 2024). "On a more detailed level, there is evidence that periodontal disease could increase circulating levels of certain pro-inflammatory cytokines, including IL-6, IL-1β, and TNF-α, that were also found to be upregulated in serum samples of men with prostatitis." (PMID 37046667, 2023). "Salivary IL-1β has been consistently found to be elevated in subjects with periodontal disease." (PMID 36791096, 2023). "Once periodontal disease is established, lipopolysaccharides and inflammatory cytokines, particularly Interleukin (IL)-1β, Prostaglandin E2 (PGE2) and Tumor Necrosis Factor (TNF)-α enhance a biologic burden which initiates the onset and progression of atherogenesis and thromboembolic events." (PMID 38077410, 2023). "Another group of biomarkers that could be used in the diagnosis of periodontal diseases is IL-1β, IL-8, MMP-13, osteoprotein, and osteoactivin." (PMID 36902030, 2023). "IL-1β plays a significant role in progression in periodontal disease." (PMID 37580412, 2023). "Overall, our results showed selective inhibition of IL-1β, TNF-α, IL-8, MMP-2, and MMP-9 associated with hesperidin, which could represent a promising novel approach to the treatment or prevention of periodontal disease." (PMID 37373533, 2023). "Thus, IL-1β is considered to be a strong promising biomarker for the early diagnosis of periodontal disease." (PMID 35368315, 2022). "Increased IL-1β in GCF has been considered as a sign of development of periodontal disease." (PMID 35162556, 2022). "Higher IL-1β levels of GCF are seen as a sign of periodontal disease, and studies proved that periodontal tissue breakdown may be controlled by regulating IL-1β expression." (PMID 35502340, 2022).
periodontal disease (continued). "It plays a paramount role in periodontal disease and alveolar bone destruction by producing proinflammatory mediators such as IL-1β, IL-6, and TNF-α, which are multifunctional cytokines produced by lymphocytes, monocytes, and fibroblasts with extensive biological activities." (PMID 35911651, 2022). "IL-1β has a crucial role in activating proteinase, collagenase, stimulating the production of prostaglandin E2, and enhancing bone resorption and degradation of the extracellular matrix in periodontal diseases." (PMID 35986791, 2022). "IL-1β and Pg indeed reflected periodontal status and may be valuable targets for predicting periodontal disease." (PMID 34001101, 2021). "This, together with the high sensitivity and specificity of IL-1β for periodontal disease reported here, suggests that IL-1 could be useful surrogate indicators for the presence of periodontal disease and inflammation." (PMID 34199256, 2021). "Local expression of tumour necrosis factor (TNF), interleukin-1β (IL-1β), and IL-6 due to inflammation triggered by bacteria involved in periodontal disease might promote and exacerbate ASCVD." (PMID 34911523, 2021). "Significantly higher levels of IL-1β, IL-6, IL-8, and IL-10 were found in constipated subjects with GB from this study, indicating an ongoing inflammatory process and the progression of periodontal disease." (PMID 33717115, 2021). "Thus, to mimic in vitro the inflammatory microenvironment in periodontal disease, we used IL-1β as inductor and enhancer of the proinflammatory response on primary gingival fibroblasts." (PMID 34035660, 2021). "The role of NGAL in periodontal disease pathogenesis, as regulated by IL-1β and IL-10, could be conjectured within the limitations of this study, as supported by the increased serum levels progressing from health to disease." (PMID 32997091, 2020). "As a chronic inflammation caused by periodontal pathogen infections, periodontal disease could increase the levels of C-reactive protein, IL-6, IFN-γ, and IL-1β." (PMID 32802852, 2020). "Indeed, IL1β is one of the inflammatory mediators highly involved in the pathogenesis of periodontal diseases." (PMID 33081038, 2020). "The studies show that the IL-1β rs1143627 polymorphism is not related to periodontal disease susceptibility." (PMID 31900383, 2020). "This study aimed to determine serum and salivary levels of neutrophil gelatinase-associated lipocalin (NGAL) and evaluate NGAL correlation with key anti-interleukin 10 (IL-10) and pro-inflammatory (IL-1β) cytokines in different severities of periodontal diseases." (PMID 32997091, 2020). "IL-1β in saliva or gingival crevicular fluid has even been speculated as a potential biomarker for periodontal disease." (PMID 31685946, 2020). "TNF and IL-1β are well-known key cytokines for periodontal disease." (PMID 31921182, 2019). "We propose that there is a correlation between IL-37 and IL-1β levels and periodontal disease, and levels of IL-37 and IL-1β correlation may be an important parameter to evaluate the efficiency of the treatment of aggressive periodontal disease." (PMID 31308830, 2019). "IL-1β in gingival crevicular fluid (GCF) is a marker of inflammation in periodontal disease." (PMID 30206230, 2018). "It is well known that IL-1β is the key inflammatory cytokine in periodontal diseases and that the elevated expression of IL-1β is closely related to the manifestations of the disease; hence, GFs in inflamed periodontal lesions are considered to be seriously affected by locally secreted IL-1β." (PMID 29932110, 2018). "Wara-Aswapati described a hypothesis that, HCMV plays a role in the pathogenesis of periodontal disease by the ability of its immediate early proteins to strongly transactivate IL-1β gene expression." (PMID 29036216, 2017).
periodontal disease (continued). "An increasing number of studies have examined the association between IL-1β rs1143627 polymorphism and periodontal disease, but as far as we know, no meta-analyses have been carried out about this issue yet." (PMID 28404906, 2017). "The current study was the first meta-analysis designed to investigate the correlation of IL-1β rs1143627 polymorphism with the risk of periodontal disease, and revealed a negative result, showing the lack of significant association." (PMID 28404906, 2017). "Our meta-analysis, based on 8 eligible case-control studies, demonstrated that there was no obvious association of IL-1β rs1143627 polymorphism with periodontal disease susceptibility in total analysis." (PMID 28404906, 2017). "IL-1β rs1143627 polymorphism is not related to periodontal disease susceptibility in the overall population based on the current evidence, but further studies are required in more large scale sample size with risk factor adjusted." (PMID 28404906, 2017). "Cytokine participation in periodontal disease is well documented and these substances, particularly TNF-α and IL-1β, may amplify the inflammatory response causing tissue destruction and bone loss." (PMID 27116554, 2016). "A comparison of GCF IL-1β levels between periodontally diseased patients and healthy subjects was conducted in order to explain the suitability of using IL-1β as a biomarker for periodontal disease progression." (PMID 28074077, 2016). "IFN-γ and IL-1β were significant for leprosy reactions and periodontal diseases." (PMID 26339136, 2015). "Several studies have shown a relationship between periodontal disease and genetic factors, including polymorphisms in interleukin (IL)-1, interferon-γ, IL-6, matrix metalloproteinase (MMP)-9, tissue inhibitor of MMP-2, vitamin D receptor, IL-1α, and IL-1β." (PMID 23050158, 2012). "Results obtained in this study indicate that increased concentrations of salivary IL-1β and IL-6, rather than being caused by local inflammation, periodontal disease and smoking, reflect local production of these cytokines in cancer tissue." (PMID 21743397, 2012). "The main finding of this study was that the investigated aerobic training protocol did not attenuate the progression of periodontal disease, as evidenced by the clinical evaluation of alveolar bone loss and the analysis of the inflammatory profile using the IL-1β test." (PMID 37936877, 2023). "Moreover, it has been established that the concentration level of IL-1β in gingival cervical fluid (GCF) from areas affected by periodontal disease is notably high; however, on the condition that the response to treatment is favorable, the IL-1β concentration level will decrease in saliva and GCF." (PMID 35706460, 2022). "Moreover, the level of IL-1β correlates well with the clinical severity of periodontal disease." (PMID 34299815, 2021). "Increased expression of NLRP3 and AIM2 in the gingival tissues of patients with periodontal disease is positively correlated with the levels of IL-1β and IL-18, suggesting that various inflammasomes may participate in the microbial-induced inflammation in periodontal diseases." (PMID 32385413, 2020). "Therefore, our findings support the hypothesis that not only stem cells reduce the concentration of IL-1β but also favor an increase in bone regeneration in patients with periodontal disease." (PMID 32908546, 2020). "Furthermore, a small amount of IL-1β has been shown to be beneficial for periodontal remodeling, including wound healing, whereas IL-1β overproduction has been demonstrated to play a role in periodontal disease etiologies." (PMID 33322510, 2020). "Studies concerning oral diseases, such as periodontal diseases, lichen planus or oral carcinoma, demonstrated the increased salivary levels of selected pro-inflammatory nuclear factor-κB dependent cytokines, e.g., interleukin 1β (IL-1β), interleukin 6 (IL-6), tumour necrosis factor α (TNF-α)." (PMID 33050496, 2020).